BRCA1 (BRCA1 DNA repair associated)
Diseases named in the same sentence as BRCA1 in open-access papers (continued):
Sharing a sentence is not in itself a finding about the gene and the disease.
pancreatic cancer (continued). "In this study, a total of 154 patients had germline BRCA1 or BRCA2-mutated metastatic pancreatic cancer without disease progression during at least 16 weeks of first-line platinum-based chemotherapy." (PMID 35228986, 2022). "Inhibition of this enzyme might be exploited for preventing and treating tumor diseases, such as BRCA1 and BRCA2 deficient tumors, including breast, ovarian, prostate, and pancreatic cancer." (PMID 36186578, 2022). "Pathogenetic variants in BRCA1 and BRCA2 genes (chromosome 17q21 and chromosome 13q12, respectively) predispose female carriers to an increased risk of breast, ovarian, and pancreatic cancer as well as melanoma and male carriers to an increased risk of breast and prostatic cancer." (PMID 35661074, 2022). "BRCA1 and BRCA2 (BRCA1/2) mutations are inherited in an autosomal dominant fashion and contribute to an increased risk of several cancers including breast, ovarian, and pancreatic cancers." (PMID 33419231, 2021). "In addition, genetic testing guidelines are adapted too slowly to recent findings, e.g., germline genetic testing of BRCA1/2 in patients with pancreatic cancer to facilitate individualized therapies with the PARP inhibitor olaparib." (PMID 34204522, 2021). "Furthermore, recent studies have reported that BRCA1/2 pathogenic variants potentially contribute to FPC and that the frequency of BRCA1/2, PALB2, and ATM variants in all pancreatic cancers is 7%." (PMID 33413558, 2021). "In 2005, two efforts highlighted the synthetic lethal interaction between PARP1 inhibition and loss of BRCA1 or BRCA2, which lead to the development of approved clinical PARP inhibitors in ovarian, breast or pancreatic cancer treatments in case of BRCA1 or BRCA2 loss-of-function." (PMID 34439361, 2021). "In pancreatic cancer, the early onset risk could be due to high risk genes such as CDKN2A, BRCA1, and BRCA2, or some known rare genes, while the second peak at age 40–49 matches the age of onset of Lynch syndrome." (PMID 34503195, 2021). "Herein, we aim to specifically evaluate the feasibility of BRCA1/2 testing by using an amplicon based Next Generation Sequencing (NGS) panel on a consecutive series of FFPE pancreatic tumor specimens, including FNAs, biopsies and surgical resections (tissue standard sections and macrosections)." (PMID 34200245, 2021). "The efficacy of platinum agents for pancreatic cancer with a germline BRCA/PALB2 mutation and of olaparib, a poly (ADP-ribose) polymerase (PARP) inhibitor, as maintenance therapy after first-line platinum-based chemotherapy for pancreatic cancer with germline BRCA1/2 have been shown." (PMID 33557084, 2021). "Moreover, the relative risk (RR) and cumulative incidence of pancreatic cancer for germline BRCA2 pathogenic variants are 3.5–10 and 2%–7%, and for germline BRCA1 pathogenic variants, 2.26 and 1%–3%, respectively." (PMID 34476650, 2021). "The BRCA1/2 germline mutation has been identified as the causative gene for hereditary breast and ovarian cancer syndrome (HBOC) but is also one of the causes for development of hereditary pancreatic cancer." (PMID 33562094, 2021). "This evidence offers the validity of routine sequencing of not only BRCA1/2 but also of the wide range of HR-related genes as part of biological characterization and for treatment decisions using PARPi, at least in the cases of breast and pancreatic cancer." (PMID 35008774, 2021). "BRCA1 or BRCA2 mutation can increase biliary and pancreas cancer incidence by around threefold." (PMID 34577828, 2021). "Evidence supports that risk for pancreatic cancer may be elevated as well in those with a pathogenic ATM variant, and BRCA1 is a downstream target of the ATM gene." (PMID 32793315, 2020). "Notably, however, mutations in the DDR system, including BRCA1 and BRCA2, but also ATM and PALB2, are emerging biologic targets for therapy in advanced pancreatic cancer." (PMID 33198203, 2020).
pancreatic cancer (continued). "Using multivariate Cox regression analysis, we detected eight optimal ubiquitination-related genes (RNF7, NPEPPS, NCCRP1, BRCA1, TRIM37, RNF25, CDC27, and UBE2H) and then used them to construct a risk model to predict the prognosis of pancreatic cancer patients." (PMID 33414811, 2020). "The BeSHG guidelines propose to discuss the arguments in favor of and against pancreatic cancer screening with BRCA1 carriers if they have ≥1 first-degree relative with pancreatic cancer and with BRCA2 carriers if they have ≥1 first-degree or ≥2 second-degree relatives with pancreatic cancer." (PMID 32655641, 2020). "This clinical trial provided the first evidence for the effectiveness of PARP inhibitors in the treatment of pancreatic cancer and subsequently resulted in the FDA approval of Olaparib for the treatment of germline BRCA1/2-mutated metastatic pancreatic adenocarcinomas." (PMID 33015058, 2020). "Identification of BRCA1 and BRCA2 mutations offers potential therapeutic advantages as they confer increased sensitivity to PARPi, reflecting a unique biology of BRCA-mutated pancreatic cancer cells." (PMID 33198203, 2020). "Genetic testing has also become more important for pancreatic cancer patients, as those having BRCA1/2-mutant tumors are predicted to exhibit increased therapeutic sensitivity to platinum-containing therapeutic agents and inhibitors of poly-(ADP-ribose)-polymerase (PARP)." (PMID 32707720, 2020). "In particular, five women (two of which BRCA1 carriers) presented a first-degree relative affected by pancreatic cancer and eight women (two of which BRCA1 carriers) presented a second-degree relative with pancreatic cancer." (PMID 32429297, 2020). "Prognosis between those with a BRCA1/2-related pancreatic cancer and those with an apparently sporadic cancer may be more similar if both tumors are resectable." (PMID 32793315, 2020). "BRCA1/2 and PALB2 are known to be associated with an increased risk for pancreatic cancer." (PMID 32793315, 2020). "In total, 113 consecutive individuals with personal or family history of breast, ovarian, or pancreatic cancer and without P/LP variants in BRCA1 and BRCA2 genes were analyzed." (PMID 32957588, 2020). "However, Brca1 and Brca2 are also involved among the most common genetic lesions in familial pancreatic cancer patients." (PMID 31480737, 2019). "Several studies reported increased cancer risk in BRCA1 mutant carriers, although the association between BRCA1 and pancreatic cancer predisposition is not well-established." (PMID 31877165, 2019). "To determine if the role of PALB2 as a linker between BRCA1 and BRCA2 is critical for BRCA1/2-mediated tumor suppression, we generated Palb2 mouse pancreatic cancer models and compared tumor latencies, phenotypes and drug responses with previously generated Brca1/2 pancreatic cancer models." (PMID 31877165, 2019). "Thus, we generated mouse models of pancreatic cancer by inactivation of Palb2, Brca1 or Brca2 genes specifically in the pancreas and compared the resulting tumor latencies, histo-pathologies, anticancer drug responses and immune cell infiltration." (PMID 31877165, 2019). "Particularly, the age for pancreatic cancer diagnosis in BRCA1 families is significantly lower than in BRCA2 families and general populations, whereas short-term prognosis for patients in BRCA2 families is significantly better than for other groups of patients." (PMID 30736435, 2019). "Moreover, 11 of these individuals without a report of pancreas screening on file harbored a deleterious BRCA1 or BRCA2 mutation and a family history of pancreatic cancer, including one individual with six second degree relatives with the disease." (PMID 32601617, 2019). "Other research has shown similar results; 6 of the 14 people that tested positive for a pathogenic BRCA1/2 in another pancreas cancer study did not meet the NCCN's criteria for germline testing." (PMID 30186770, 2018).
pancreatic cancer (continued). "It has been reported that germline mutations in BRCA1 and BRCA2 predispose to pancreatic cancer." (PMID 29069866, 2017). "It is clear that BRCA1/2 mutations are evident in many familial breast-pancreas cancer families and that carriers of the BRCA2 mutation have an increased risk of developing pancreatic cancer." (PMID 26236408, 2015). "Our therapy also appears to be highly effective for eradicating other types of cancers which express varying levels of FRα, including breast and pancreatic cancers expressing WT and/or mutant BRCA1 and/or BRCA2 (Schutsky and Powell, 2014, unpublished observations)." (PMID 26359629, 2015). "The majority of studies examining the prevalence of pancreatic cancer in BRCA1 mutated patients have shown no increased risk, however, others have estimated a 2- to 2.5-fold increased risk." (PMID 24624093, 2014). "In this context, the HBCx-17 model could improve preclinical assays of PARP inhibitors that are usually done in BRCA1/2 knockout mice or in pancreatic cancer cells." (PMID 20877358, 2010). "In a similar manner, mutations in BRCA1 and BRCA2 may explain in part the cluster seen between prostate, breast, ovarian, and possibly pancreatic cancer." (PMID 15630470, 2004). "DNA damage repair deficiency, for example, through BRCA1/BRCA2, ATM or PALB2 loss, is seen in ∼15% of all pancreatic tumours and may represent a window of opportunity for radiotherapy in these patients due to increased radiosensitivity as a result of genomic instability." (PMID 38979684, 2024). "Indeed, the pancreatic cancer risk was significantly increased in male relatives of BRCA2 carriers (RR = 4.34) but not relatives of BRCA1 carriers." (PMID 36861435, 2023). "The Pancreas Cancer Olaparib Ongoing (POLO) trial, demonstrated that Olaparib maintenance therapy prolongs progression-free survival compared to placebo in patients with pancreatic ductal adenocarcinoma and germline BRCA1/2 mutations after platinum-based first-line chemotherapy." (PMID 37710166, 2023). "No BRCA1 protein truncating variant was detected in pancreatic cancer patients from Pakistan." (PMID 37951914, 2023). "Silencing circ-MTHFD1L caused a decrease in BRCA1/2 expression or other unknown changes in BRCAness-associated proteins, undoubtedly pointing out a new direction for circ-MTHFD1L as a therapeutic target for pancreatic cancer." (PMID 35459186, 2022). "However, PARP inhibitors are not as effective in pancreatic cancer, where they are used as maintenance treatment in patients with germline BRCA1/2 mutations after first-line platinum-based chemotherapy." (PMID 36358659, 2022). "In conclusion, our retrospective study found that individualized selection of chemotherapy drugs combined with sequential immunotherapy based on BRCA1 mRNA expression level could control the disease and prolong survival of patients with unresectable pancreatic cancer." (PMID 36387089, 2022). "In a study of 204 individuals with pathogenic BRCA1/2 variants, all BRCA1/2 patients irrespective of pancreatic cancer family history were recommended to undergo surveillance because the prevalence of pancreatic abnormalities was not affected by family history." (PMID 35163129, 2022). "Like BRCA1 and BRCA2 mutations, PALB2 mutation may increase the risk of pancreatic cancer." (PMID 35779338, 2022). "Our results suggest that individualized selection of chemotherapy combined with sequential immunotherapy according to BRCA1 mRNA expression level in the treatment of unresectable pancreatic cancer could control the disease and have controllable adverse reactions." (PMID 36387089, 2022).
pancreatic cancer (continued). "Based on the available literature, it is estimated that 17 to 25% of pancreatic cancer harbor somatic PVs in one of the genes involved in DDR, mainly those implicated in homologous recombination DNA damage response and repair (HR), such as BRCA1, BRCA2, ATM, PALB2, ATRX, and RAD51." (PMID 35563100, 2022). "Since abnormalities in the homologous recombination deficiency (HRD)-related genes are observed in pancreatic cancer, clinical trials to verify the efficacy of the poly (ADP-ribose) polymerase (PARP) inhibitors have been conducted in pancreatic cancer patients with germline mutations in BRCA1/2." (PMID 33562094, 2021). "MGPTs generally cover at least 10 common HR-related genes such as ATM, BARD1, BRCA1, BRCA2, BRIP1, CHEK2, NBS1 (NBN), PALB2, RAD51C, and RAD51D, all of whose germline alterations are associated with BRCAness phenotypes for predisposition to breast, ovarian, prostate, or pancreatic cancer." (PMID 35008774, 2021). "Pathogenic BRCA1/2 variants do not present LOH in all pancreatic cancers." (PMID 32295625, 2020). "The NCCN clinical practice guideline in genetic high-risk assessment for breast, ovarian, and pancreatic cancer does not recommend pancreatic cancer screening for BRCA1 and BRCA2 mutation carriers in the absence of a close family history of exocrine pancreatic cancer." (PMID 32655641, 2020). "Patients with DNA-damage response genes (DDR)-related pancreas cancer (BRCA1/2 or other DNA-damage related genes) may have improved outcomes secondary to increased sensitivity to DNA-damaging drugs (platinum chemotherapy/ poly ADP ribose polymerase (PARP)-inhibitors)." (PMID 32793315, 2020). "The observed dichotomy in precursor lesions between the Brca1-deficient and Brca2-deficient tumors and the mixture of both in Palb2 deficient tumors might provide insights into mechanisms underlying the higher pancreatic cancer incidence and aggressiveness in BRCA2 vs BRCA1 mutation carriers." (PMID 31877165, 2019). "Inherited mutations in the BRCA1 and BRCA2 (BRCA1/2) cancer susceptibility genes convey high lifetime risks of BC and OC, in the range of 40–66% and 13–46%, respectively, as well as, increased susceptibility for other malignancies, such as prostate and pancreatic cancers." (PMID 31771539, 2019). "Moreover BRCA1 and BRCA2 mutations resulting in DNA damage repair deficiency and increasing especially the risk for breast and ovarian cancer are the most common causes of familial pancreatic cancer." (PMID 31540286, 2019). "In colorectal cancer and pancreatic cancer, no specific mutational patterns have been detected, although some tumors with defective DNA repair genes, including DNA mismatch repair genes, DNA polymerase genes, or BRCA1/2, exhibit characteristic patterns." (PMID 26083936, 2015). "In addition, an analysis of 66 familial pancreatic cancer patients from NFPTR kindred with three or more relatives with PDAC did not identify any deleterious BRCA1 germline mutations in these patients." (PMID 24624093, 2014). "To investigate the potential synergistic effect of OFD1 inhibition and olaparib treatment in pancreatic cancer, we used two pancreatic PDX models derived from patients with BRCA1/2 wild-type tumors." (PMID 40764600, 2025). "In a study sequencing 336 pancreatic cancer specimens, potentially actionable targets were identified in 26% of cases, including alterations in ERBB2, BRCA1 or BRCA2, BRAFV600E, ROS1, and ALK1." (PMID 40227779, 2025). "Here, in preclinical models of pancreatic cancer, the authors identify OFD1 as a transcriptional regulator of BRCA1 via the DREAM complex and as a potential therapeutic target in combination with PARP inhibition." (PMID 40764600, 2025). "In pancreatic cancer, KLF5 acts on the TCCCCTTCCC sequence in the promoter of the downstream target BRCA1, promoting transcription and increasing BRCA1 expression levels." (PMID 40936898, 2025).
pancreatic cancer (continued). "Intriguingly, the immunofluorescence assay revealed a reduction in the foci of BRCA1 and Rad51, two crucial proteins involved in DNA repair, in NLRP4-knockdown pancreatic cancer cells 6 h after olaparib removal." (PMID 39187531, 2024). "BRCA1 and BRCA2 methylation was significant and correlated with decreased survival in patients with operable pancreatic cancer." (PMID 38577595, 2024). "In the recent study we have tried to evaluate, for the first time, the prognostic value of BRCA1 and BRCA2 methylation in the cell-free DNA of pancreatic cancer patients." (PMID 38577595, 2024). "These pathogenic variations in the BRCA genes, found in families with a background of familial pancreatic cancer (FPC), are commonly located in BRCA1’s EXON10 and BRCA2’s EXON11." (PMID 38809921, 2024). "Using this method, we examined CNVs in BRCA1 and BRCA2 in 293 Chinese patients with ovarian or pancreatic cancer." (PMID 38274092, 2023). "This cohort study compares the outcomes of patients with BRCA1 and BRCA-related pancreatic cancers using 2 large data sets." (PMID 38010655, 2023). "The clinical importance of genetic testing of BRCA1 and BRCA2 in breast, ovarian, prostate, and pancreatic cancers is widely recognized." (PMID 35420638, 2022). "In this review, we aim to describe the role of certain genes (BRCA1 and BRCA2) in the development of pancreatic cancer and the current and future research efforts underway to treat this subtype of disease." (PMID 35626055, 2022). "The present study provides data on germline variations of BRCA1/2 and HR-DDR genes in a large sample of Han Chinese patients with pancreatic cancer." (PMID 35171259, 2022). "The discovery of BReast CAncer gene 1 (BRCA1) and BRCA2 in the 1990s revolutionized the way we research and treat breast, ovarian, and pancreatic cancers." (PMID 35626055, 2022). "Because of their crucial role in the DNA double-strand break repair process via homologous recombination (HR), BRCA1 and BRCA2 (BRCA1/2) are among the most tested genes in patients with breast, ovarian, prostate, or pancreatic cancer." (PMID 36171877, 2022). "The discovery of BRCA1 and BRCA2 in the 1990s revolutionized the way we research and treat breast, ovarian, and pancreatic cancers." (PMID 35626055, 2022). "Independent of familial history, germline or somatic mutations in BRCA1 and BRCA2 genes occur in 5–10% of patients with pancreatic cancers, with a prevalence for BRCA2 ranging from 3.6–7% and <3% for BRCA1." (PMID 34200245, 2021). "The involvement of these targets of E2F7, such as BRCA1, CDC25A, CDC6 in pancreatic cancer deserves further investigation." (PMID 35201478, 2021). "For example, BRCA1/BRCA2 testing criteria have broadened and now include additional indications such as personal history of pancreatic cancer and unaffected women with only minimal family history." (PMID 31853058, 2020). "Recently, cancer genetic predisposition and precision medicine have found a contact point, thanks to the discovery of the therapeutic potential of PARP inhibitors in BRCA1/2 PV/LPV carriers, at first in OC and then in BC, prostate, and pancreatic cancers." (PMID 32046255, 2020). "We compared the histo-pathology of the pancreatic tumors that developed among Palb2-KPC, Brca1-KPC and Brca2-KPC to those of KPC animals." (PMID 31877165, 2019). "Two male relatives, one from a BRCA1 positive family and one from a BRCA2 positive family, were diagnosed with both breast and pancreatic cancer." (PMID 26236408, 2015). "In pancreatic cancer, autoantibody frequency to three TAAs (PARP1, BRCA1 and BRCA2) were 0% (0/41), 7.3% (3/41) and 0% (0/41)." (PMID 25865228, 2015). "Male tumors related to BRCA1 and BRCA2 include breast, melanoma, stomach, prostate, colon and pancreatic cancer." (PMID 17254323, 2007). "The frequency of BRCA1 methylation in our AML patients is similar to that of patients with breast, ovarian and pancreatic carcinomas." (PMID 17047656, 2006).